ENSG00000282885 (novel transcript)
Gene: Long non-coding RNA gene on chromosome 14 (49,860,314 to 49,868,199, reverse strand). Ensembl gene ENSG00000282885.
Gene Ontology:
Biological process: SRP-dependent cotranslational protein targeting to membrane, signal sequence recognition
Cellular component: signal recognition particle, endoplasmic reticulum targeting